STAM2 (signal transducing adaptor molecule 2)
Description:
Involved in intracellular signal transduction mediated by cytokines and growth factors. Upon IL-2 and GM-CSL stimulation, it plays a role in signaling leading to DNA synthesis and MYC induction. May also play a role in T-cell development. Involved in down-regulation of receptor tyrosine kinase via multivesicular body (MVBs) when complexed with HGS (ESCRT-0 complex). The ESCRT-0 complex binds ubiquitin and acts as a sorting machinery that recognizes ubiquitinated receptors and transfers them to further sequential lysosomal sorting/trafficking processes (By similarity).
Synonyms: HBP; STAM2A; STAM2B
Tractability: Antibody: UniProt places it where antibodies can reach, with high confidence. PROTAC: ubiquitination databases record sites on it; its protein half-life has been measured.
Gene: Protein-coding gene on chromosome 2 (152,116,801 to 152,175,771, reverse strand). Ensembl gene ENSG00000115145.
Subcellular location: Cytoplasm; Early endosome membrane
Subcellular location (Human Protein Atlas): Vesicles; Cytosol; Nucleoplasm
Pathways (Reactome):
Signal Transduction: EGFR downregulation; Negative regulation of MET activity; RHOU GTPase cycle
Vesicle-mediated transport: Cargo recognition for clathrin-mediated endocytosis; Clathrin-mediated endocytosis; Endosomal Sorting Complex Required For Transport (ESCRT)
Disease: InlB-mediated entry of Listeria monocytogenes into host cell
Metabolism of proteins: Ub-specific processing proteases
Gene Ontology:
Molecular function: protein binding; phosphatidylinositol binding; ubiquitin binding
Biological process: macroautophagy; membrane fission; multivesicular body assembly; protein transport to vacuole involved in ubiquitin-dependent protein catabolic process via the multivesicular body sorting pathway; signal transduction
Cellular component: cytoplasm; cytosol; endocytic vesicle; ESCRT-0 complex; early endosome membrane
Genetic constraint (gnomAD): Loss-of-function variants: 34 observed, 44.4 expected, observed/expected ratio (o/e) 0.77, 90% interval 0.58 to 1.02. The upper end of that interval is the gene's LOEUF score, 1.02, which puts it in group 4 of 6, group 1 being the genes least tolerant of losing a copy. Missense variants: 441 observed, 492.66 expected, observed/expected ratio (o/e) 0.9, 90% interval 0.83 to 0.97. Synonymous variants: 164 observed, 176.51 expected, observed/expected ratio (o/e) 0.93, 90% interval 0.82 to 1.06.
Homologues: Orthologues: chimpanzee STAM2 (99% identical), macaque STAM2 (99% identical), pig STAM2 (94% identical), dog STAM2 (93% identical), guinea pig STAM2 (88% identical), mouse Stam2 (86% identical), rat Stam2 (83% identical), rabbit STAM2 (83% identical), tropical clawed frog stam2 (70% identical), zebrafish stam2 (61% identical), Drosophila melanogaster Stam (42% identical), Caenorhabditis elegans stam-1 (28% identical), and 3 more. Paralogues in human: STAM (56% identical), HGS (26% identical), TOM1L2 (21% identical), TOM1 (19% identical), TOM1L1 (16% identical), GGA1 (16% identical), GGA3 (16% identical), GGA2 (14% identical), WDFY1 (8% identical), WDFY2 (7% identical).
Diseases named in the same sentence as STAM2 in open-access papers:
STAM2 is named in the same sentence as 8 diseases in open-access papers, as found by Europe PMC text mining. Sharing a sentence is not in itself a finding about the gene and the disease. The quoted sentences say what the papers report.
alopecia (2 papers, 2013 to 2025). Hair loss usually from the scalp. "However, since rs3820706 is strongly linked to rs16830728, which is located within a gene encoding a signal transducing adaptor molecule 2 (STAM2), we cannot exclude the possibility that STAM2 is a candidate gene for chemotherapy-induced alopecia." (PMID 24025145, 2013). "STAM2, which is involved in signaling pathways, has been identified as a potential candidate gene for chemotherapy-induced alopecia." (PMID 41380997, 2025). "STAM2 has been identified as a potential candidate gene for chemotherapy-induced alopecia, indicating that the pathogenesis of chemotherapy-induced alopecia may be focused on the stage of hair follicle appearance." (PMID 41380997, 2025).
breast carcinoma (1 paper, 2025). "SNPs near genes such as CACNB4, STAM2, and ABCB1 are associated with a higher risk of CIA, particularly in breast cancer cohorts." (PMID 40227705, 2025).
gastric cancer (1 paper, 2024). A primary or metastatic malignant neoplasm involving the stomach. "STAM2 knockdown has been reported to inhibit proliferation, migration, and invasion by affecting the JAK2/STAT3 signaling pathway in gastric cancer." (PMID 39060946, 2024).
metastatic tumors (1 paper, 2018). "Human-specific gene expression of SNAI1, GSC, FOXC2, KRT19, and STAM2, presumably originating from DTCs, was detected in the BM of all xenograft mice that also developed metastatic tumors." (PMID 29291741, 2018).
tumor (2 papers, 2024 to 2025). "Furthermore, STAM2 significantly influences the expression of MMP2/MMP9, as well as the phosphorylation of JAK2/STAT3 in cancer cells, thereby enhancing tumor malignancy." (PMID 40149859, 2025).
STAM2 also shares sentences with these, for which no sentence is quoted: cancer (1 paper); leukemia (1); melanoma (1).